IL1A (interleukin 1 alpha)
Diseases named in the same sentence as IL1A in open-access papers (continued):
Sharing a sentence is not in itself a finding about the gene and the disease.
Hepatitis (8 papers, 2012 to 2024). Inflammation of the liver. "High gene expression levels of CXCL3, CXCL8, and IL1A also correlate with HCV-associated liver inflammation, cirrhosis, and HCC." (PMID 34497613, 2021). "The pathogenic roles of IL-1α, TNF-α, IFN-γ, and IL-6 in Con A-induced hepatitis have been extensively established in previous studies 39-42." (PMID 32641985, 2020). "Cd can activate the NLRP3 inflammasome, promoting liver inflammation and hepatitis, particularly severe during early estrus, by increasing TNF-α, MCP-1, and pro-inflammatory cytokines such as IL-1α, IL-1β, and IL-18." (PMID 39255638, 2024). "In our study, the elimination of KCs completely protects against Con A-induced hepatitis by decreasing serum inflammatory cytokines such as IL-1α, TNF-α, IFN-γ, MCP-1, IL-12, and IL-6, relevant to Con A-induced hepatitis 39-42." (PMID 32641985, 2020). "The pro-inflammatory markers IL-1α, IL-1β, IL-6, TNF, ICAM-1, and VCAM-1 were all significantly upregulated under both hepatitis models." (PMID 29445190, 2018). "Similarly, increased IL-1α levels in AVH-E vs recovery in the current series of patients and increased levels of IL-1β and TNF-α in AVH-E and recovered cases in our previous report suggest their probable role in the pathogenesis of hepatitis and hepatocytic injury." (PMID 22384080, 2012). "The transcriptomic profile of 284 genes involved in inflammation, cell signaling, and remodeling showed that the expression of IL-1 family members, IL-1α, IL-1β, and IL-18, was not varied between WT and IL-33 KO mice following L2-MHV3 hepatitis." (PMID 28607531, 2017).
Hyperglycemia (8 papers, 2008 to 2024). An increased concentration of glucose in the blood. "To obtain more comprehensive details about the inflammatory processes caused by hyperglycemia, we examined the expression of TNF-α, IL-6, IL-8, and IL-1α." (PMID 33147748, 2020). "After 17 hours post-activation, hyperglycemia and hypoxia are required to maintain a high expression of IL-1A." (PMID 31415598, 2019). "In sharp contrast, hypoxia had a huge effect as the IL-1a gene expression was circa five fold higher for cells cultivated in hyperglycemia and normoglycemia." (PMID 31415598, 2019). "Further characterization of the inflammatory response to hyperglycemia, as well as nerve degeneration, is required to validate the role of other key cytokines important in corneal homeostasis, including IL-1α and IL-6." (PMID 30470798, 2018). "Relative to the effect of hyperinsulinaemia alone, combined hyperglycaemia and hyperinsulinaemia led to a further increase in IL1A, IL1B and CCL3 mRNA levels." (PMID 18290856, 2008). "Combined hyperglycaemia and hyperinsulinaemia led to enhanced IL1A, interleukin-1 beta (IL1B) and CCL3 mRNA levels upon LPS stimulation." (PMID 18290856, 2008). "In this work, we show that hyperglycemia induces tubular production of IL-1α that may contribute to the pathogenesis of tubulointerstitial injury in DN." (PMID 32733443, 2020). "Persistent hyperglycemia triggers expression of various proinflammatory cytokines and chemokines, including interleukin-6 (IL-6), interleukin-8 (IL-8), interleukin-1α (IL-1α), and tumor necrosis factor-alpha (TNF-α, which in turn leads to an increase in the inflammatory response." (PMID 33147748, 2020). "Finally, there was a significant interaction between hyperglycaemia and hyperinsulinaemia on post-clamp mRNA levels of IL1A and CCL3 (Pinteraction < 0.05)." (PMID 18290856, 2008). "Thus, local production of IL-1α and autocrine IL-1 signaling during hyperglycemia and the following uncontrolled deposition of ECM proteins such as fibronectin and α-SMA may play a role in the progression of DKD by promoting or intensifying renal fibrosis." (PMID 32733443, 2020). "The impact of hypoxia and hyperglycemia on the gene expression of TNF- α, IL-1a, IL-6 and GM-CSF was analyzed in detail and compared to the results obtained with the microarray." (PMID 31415598, 2019). "In contrast, hyperinsulinaemia enhanced LPS-induced gene expression of several cytokine genes, and its effect on mRNA induction of IL1A, IL1B and CCL3 was especially clear in the concurrent presence of hyperglycaemia." (PMID 18290856, 2008). "Remarkably, hyperglycaemia seemed to reduce gene expression (significantly so for NFKBIA, IL1A and CCL3), whereas hyperinsulinaemia enhanced the expression of six out of eight measured inflammatory genes." (PMID 18290856, 2008). "This was true for hypo-, normo-, and hyperglycemia, with a few exceptions: there was a lack of statistical significance between observed differences for IL-1α, IL-2 and IL-4 in the hypoglycemic environment and non-significant differences for IL-2 in hyperglycemia." (PMID 38542084, 2024). "Despite this, mRNA levels of the proinflammatory genes IL1A and CCL3 were also lower, and NFKB1 was also not up-regulated after hyperglycaemia." (PMID 18290856, 2008). "In order to obtain insight into the inflammatory processes induced by hyperglycemia, we examined the expression levels of four proinflammatory cytokines, namely, TNF-α, IL-6, IL-8, and IL-1α, under hyperglycemic conditions with or without anthocyanin-rich sour cherry extract." (PMID 33147748, 2020).
inflammatory skin disease (8 papers, 2017 to 2024). Inflammatory skin disorders covers a broad category that includes many conditions ranging in severity, from mild itching to grave medical health complications These disorders are common in people of all ages and races. "Additional studies regarding the effect of UVB-induced IL-22 production and IL-22Rα expression on the production of IL-1α, IL-6, and IL-18 will provide a basis for further understanding the role of IL-22 in the control of inflammatory skin disease." (PMID 28558005, 2017). "In the development of some inflammatory skin disorders with the release of interleukins from epidermal cells, one of these, IL1α, has an important role." (PMID 28611508, 2017). "Given that IL-1α and IL-6 are involved in the pathogenesis of skin diseases caused by proliferation of keratinocytes, IL-22-dependent regulation of UVB-induced IL-1α, IL-6, and IL-18 production may be important in the mechanism of inflammatory skin diseases." (PMID 28558005, 2017). "IL-1α and IL-1β, mainly produced by the keratinocytes in the skin, as well as TNF-α are key inflammatory cytokines in inflammatory skin diseases such as dermatomyositis and pemphigus, as well as experimental pemphigoid disease." (PMID 31001258, 2019).
liver diseases (8 papers, 2015 to 2025). "Clotting factor deficiencies may also be due to reduced synthesis for hepatic disease, increased clearance in enlarged spleen, or accelerated consumption in a state of low-grade intravascular coagulation and fibrinolysis, supported by IL-1α, TNF-α, and IL-6." (PMID 36498496, 2022). "Since IL-1α, IL-1β, IL-33, and IL-36 are implicated in vivo during liver diseases, the efficiency of the therapeutic approaches based on targeting a cytokine by the other members may be affected." (PMID 31507607, 2019). "Current researches have demonstrated that TNF, IL-1α/β, IL-1Ra, IL-6, IL-18, IL-33, IL-36, IL38, CCL2 and CCR2 are closely associated with liver disorders." (PMID 41333471, 2025). "Inflammasome triggers or amplify liver diseases by releasing pro-inflammatory cytokines such as IL-1β, IL-1α, IL-18, and also through other inflammatory mediators such as High Mobility Group Box 1 (HMGB1)." (PMID 32431709, 2020). "In the context of liver diseases, cytokines have been assigned fundamental properties reflecting common function, including proinflammatory cytokines (e.g. IL‐1α, IL‐1β, TNF‐α, and IL‐2), immunoregulatory cytokines (e.g. IFN-γ), and anti-inflammatory cytokines (e.g. IL-10 and IL-4)." (PMID 33841403, 2021). "In addition, many studies on the IL-1α/IL-1R axis in liver disease have high patient numbers." (PMID 35911735, 2022).
lung disease (8 papers, 2016 to 2023). "Many studies had revealed that the proinflammatory factory like TNF-a, IL-1a and IL-6 have an effect on the lung disease." (PMID 28521806, 2017). "Studies utilizing the β-ENaC murine model of CF-like lung disease have observed the presence of mucus obstruction and airway neutrophilia in germ-free conditions, with “sterile” inflammation in the CF airway triggered by IL-1α released from necrotic AEC." (PMID 32328066, 2020). "Genes showing altered expression include a number of genes known to play important roles in lung disease such as α1-antitrypsin (SERPINA1), transforming growth factor β 1 (TGFβI), interleukin 1 receptor 1 (IL1R1) and IL6, IL8, IL1B, IL1A." (PMID 28335732, 2017).
metabolic syndrome (8 papers, 2018 to 2025). A cluster of metabolic risk factors for CARDIOVASCULAR DISEASES and TYPE 2 DIABETES MELLITUS. "Both IL-1α and IL-1β gene polymorphisms have been reported to be associated with central obesity and metabolic syndrome in a population with coronary heart disease in an epidemiologic study." (PMID 31182982, 2019). "When comparing within metabolic syndrome subjects, serum levels of IL-10, IL-1α, and TNF-α revealed a trend towards higher levels in subjects with vitamin D deficiency." (PMID 32178228, 2020). "Additionally, in individuals with metabolic syndrome, 4 weeks of consuming anthocyanin-rich berries significantly down-regulated the expression of NF-κB-dependent genes, including TNF-α, IL-6, IL-1A, PCAM-1, and COX-2." (PMID 41156509, 2025). "Therefore, we have decided to search for the relationship between the TNFα gene polymorphisms and serum levels of proinflammatory cytokines (IL-1α, IL-1β, IL-6, TNFα, IFNγ) and CRP in women with metabolic syndrome." (PMID 30383538, 2018).
migraine (8 papers, 2022 to 2024). "It has been found that the level of IL-1α is elevated in the blood of children suffering from migraine with aura (MA)." (PMID 37755358, 2023). "Of the 25 overlapping genes/loci, 6 genes/loci were associated with more than 2 phenotypes in HPGDB (COMT, OPRD1, IL1A, IL1B, TSPAN2/NGF, GDF5), and 15 genes were associated with migraine." (PMID 37144689, 2023). "In a study of the IL-1α gene, holders of genotype T/T in the promoter region (889 base pairs upstream) have a significantly earlier onset of migraine than the wild types C/C and C/T, which are observed more frequently in migraine with aura." (PMID 37176049, 2023). "The aim of this study was to investigate whether functional polymorphisms in the IL-1 family (IL-1α, IL-1β and IL-1RN), IL-6 and TNF-α genes may influence the response to oral NSAID administration or triptans during migraine attacks." (PMID 36614097, 2022). "Our results indicated that the effect of migraine in increasing the risk of AD development might be mediated by TNFα, while IL-1α, IL-1β, and IL-6 do not play a role in this process." (PMID 38903170, 2024). "Increased levels of IL-1α can induce the recruitment and activation of additional immune cells, perpetuating a cycle of inflammation that could potentially contribute to the pathogenesis of migraines." (PMID 39170074, 2024). "However, further research is needed to fully elucidate the mechanistic link between cigarette smoke, IL-1α and CDCP1 elevation, and migraine pathogenesis." (PMID 39170074, 2024). "Blood levels of IL-1α were increased in children with migraine compared to controls, and IL-1a concentrations were significantly higher in patients with migraine with aura than in patients without migraine with aura." (PMID 39416954, 2024). "Studies indicate that children experiencing migraine have raised plasma levels of IL-1α compared to those who do not suffer from migraine, and these concentrations are markedly higher in individuals with migraine accompanied by aura compared to those without aura." (PMID 37755358, 2023).
myeloma (8 papers, 2019 to 2025). "In myeloma studies, IL-1a and IL-1β have been shown to work synergically with IFN-γ to induce tumor-killing activity in tumor-infiltrating macrophages." (PMID 40244135, 2025). "Cancer cells including human multiple myeloma can induce cells to generate interleukins (IL-1α and IL-1β) or it can directly release IL-1α and IL-1β within the tumor microenvironment." (PMID 35399416, 2022). "Th17 cells can also stimulate the secretion of IL-1α, IL-13, IL-17, and IL-23, as well as promoting myeloma cell growth, colony formation, and growth of xenografts in mouse models of MM20." (PMID 36224246, 2022). "The cancer‐suppressive effect of IL‐1β was confirmed in a mouse model for myeloma showing that IL‐1β (as well as IL‐1α) neutralization by anakinra severely impaired myeloma clearance by tumor‐specific Th1 cells and tumor‐infiltrating macrophages." (PMID 32770571, 2020).
squamous cell carcinoma (8 papers, 2006 to 2025). A carcinoma arising from squamous epithelial cells. "We evaluated the association of IL-1α rs3783553 polymorphism with risk of recurrence of squamous cell carcinoma of the oropharynx (SCCOP) in a cohort of 1008 patients." (PMID 27121322, 2016). "IL-1α was localized to the neoplastically transformed squamous epithelium in squamous cell carcinoma and to neoplastically transformed columnar epithelium lining the endocervical and the glandular epithelium of the endocervical glands in adenocarcinomas." (PMID 25237386, 2014). "Using immunohistochemistry, IL-1α was localized to the neoplastically transformed squamous, columnar and glandular epithelium in all cases of squamous cell carcinoma and adenocarcinomas explants studied." (PMID 25237386, 2014).
ulcerative colitis (8 papers, 2012 to 2024). An inflammatory bowel disease involving the mucosal surface of the large intestine and rectum. "The inflammatory cytokine gene (IL1α) is associated with ulcerative colitis." (PMID 37927593, 2023). "We first analyzed the expression levels of GLI1, IL-1A, and IL-1B with the published dataset and found that they were increased in ulcerative colitis compared to health tissues." (PMID 37889976, 2023). "IL1R2 is a decoy receptor that IL1A can bind in order to prevent IL1A mediated signal transduction and may play protective roles in chronic inflammatory diseases like ulcerative colitis and liver cirrhosis." (PMID 33995488, 2021). "One study reported the use of mucosal proinflammatory gene signatures (TNF, interleukin 1 alpha [IL1A], regenerating family member 1 alpha [REG1A], IL8, interleukin 1 beta [IL1B], and leukocyte immunoglobulin-like receptors A [LILRA]) in patients with ulcerative colitis." (PMID 39483464, 2024). "Similarly, aberrant regulation of IL-1α and IL-1β is a contributing mechanism in persistent inflammation in IBD, while alterations in the expression of genes involved in fatty acid metabolism may contribute to the pathophysiology of ulcerative colitis." (PMID 23382912, 2013).
Autoimmunity (7 papers, 2013 to 2025). The occurrence of an immune reaction against the organism's own cells or tissues. "Th17 cells, involved in autoimmunity and inflammation, can emit interleukins 17 and 22 in reply to IL-1α stimulation, and we have shown the increased level of IL-17 in autoimmune blistering diseases as well." (PMID 28611508, 2017). "Although the pathways have yet to be defined, taken together, these studies point to the endosomal TLRs, the proinflammatory cytokines IL-1α and IL-6 but not type I IFN as the major innate factors that drive autoimmunity following exposure to mercury." (PMID 23557436, 2013). "Mercury-induced autoimmunity, although showing clear evidence of TLR involvement does not require type I IFN, but rather shows significant dependence on proinflammatory cytokines such as IL-1α and IL-6." (PMID 23557436, 2013).
Cirrhosis (7 papers, 2015 to 2024). A chronic disorder of the liver in which liver tissue becomes scarred and is partially replaced by regenerative nodules and fibrotic tissue resulting in loss of liver function. "In a rat cirrhosis model, GA prevented an increase in the levels of proinflammatory cytokines (IL-1α and TNFα) in the plasma and the depletion of the anti-inflammatory cytokine IL-4 resulting from chronic bile duct ligation." (PMID 36720896, 2023). "A higher trend of pro-inflammatory cytokines including IL-1α, IL-1β, IL-6, IL-8, IFN-γ and TNF-α was detected in the plasma from ACLF patients than that from cirrhosis patients, as well as the anti-inflammatory cytokines including IL-4, IL-10 and IL-13." (PMID 37380987, 2023). "Moreover, significantly higher concentrations of IL-1α were observed in the group with class C cirrhosis, as compared to alcoholics without cirrhosis and the group with class A liver cirrhosis." (PMID 26448742, 2015).
endometritis (7 papers, 2009 to 2025). An acute or chronic, usually bacterial infectious process affecting the endometrium. "In particular, the expression of pro-inflammatory cytokine IL1A mRNA was significantly increased in endometritis." (PMID 33718475, 2021). "Endometritis is characterized by the high expression of CD14, TLR4, IL-1α, IL1-β, IL-6, IL-8, and TNF-α in uterine tissue and cervical mucus." (PMID 39858163, 2025). "Additionally, the expression of IL1A, as well as CXCL8, was found upregulated in cows suffering from postpartum endometritis." (PMID 39858269, 2025). "Previous studies show that mRNA of proinflammatory cytokines interleukin-1 alpha (IL1A), IL1B, IL6, and TNF and expression of chemokines IL8 and CXCL5 increased in endometrial epithelial cells during the estrous cycle and subclinical or clinical endometritis." (PMID 33324700, 2020).
Erythema (7 papers, 2012 to 2025). Redness of the skin, caused by hyperemia of the capillaries in the lower layers of the skin. "Across the three independent studies, pHCA alone or in combination with Nam showed a significant mitigation of UV‐induced erythema, barrier disruption, and levels of the surface inflammatory biomarkers IL‐1RA/IL‐1α." (PMID 39138602, 2025). "Interleukin 1 alpha (IL-1α) is a major driver of inflammation in DD, as infants with DD, heat rash and erythema show a significant increase in IL-1α levels compared to healthy infants." (PMID 35053737, 2022). "Notably, in this study, Nutroxsun® significantly lowered IL-8, IL-6, and IL-1α levels down to baseline levels in UV-exposed keratinocytes, correlating with the observed reduction in erythema." (PMID 40362239, 2025). "Interleukin-1α (IL-1α) and prostaglandin E2 mediate inflammation in skin via cytokine-dependent and arachidonic acid-dependent pathways, both of which play a role in the development of erythema and edema." (PMID 22988452, 2012). "Proinflammatory markers (including IL-1α) that are indicative of subclinical inflammation (i.e., erythema) may be useful in predicting the skin irritation potential of a skin cleansing product." (PMID 22988452, 2012). "We analyzed the correlation between the values of IL-1α, IL-1RA, CXCL-1/2, and hBD-1 measurements from psoriatic skin against the PASI and the values of erythema, induration, and desquamation, at the area of the FibroTx TAP measurements." (PMID 36936209, 2023). "The initial release of IL-1α and TNF-α starts a further cascade of pro-inflammatory chemo- and cytokines, resulting in inflammation and erythema of the skin." (PMID 35053737, 2022). "Treated sites were then exposed to 1.5 minimal erythemal dose (MED) solar simulated radiation (SSR) and had chromameter and expert grading measures for erythema, barrier integrity via TEWL, and the skin surface IL‐1RA/IL‐1α inflammatory biomarkers isolated from D‐Squame tapes." (PMID 39138602, 2025).